IL22 (interleukin 22)
Diseases named in the same sentence as IL22 in open-access papers (continued):
Sharing a sentence is not in itself a finding about the gene and the disease.
vitiligo (9 papers, 2017 to 2024). Generalized well circumscribed patches of leukoderma that are generally distributed over symmetric body locations and is due to autoimmune destruction of melanocytes. "Research has shown that IL‐22 is closely related to active vitiligo, which may cause inflammation and lead to the destruction of melanocytes." (PMID 33169883, 2021). "Therefore, we speculate that hsa‐miR‐340‐5p and hsa‐miR‐335‐5p may jointly regulate the expression of IL‐22 and cause vitiligo inflammation and melanocyte destruction." (PMID 33169883, 2021). "Previous studies have shown that IL-22 was elevated in vitiligo and related to disease extent and activity." (PMID 38361944, 2024). "One study found that the peripheral blood T-helper type 17 reaction was unbalanced in patients with vitiligo, and the plasma levels of IL-17A and IL-22 were higher healthy controls, which was consistent with our results." (PMID 33679890, 2021). "Serum levels of IL-22 are higher in vitiligo patients than in controls and are significantly increased in generalized vitiligo compared to localized disease." (PMID 34768860, 2021). "AhR activation enhanced IL-22 release in CD4+ T cells of vitiligo patients." (PMID 38361944, 2024). "Indeed, AhR expression was significantly lower in CD4+ T cells and the skin of vitiligo patients than that in healthy controls, and knockdown of AhR increased IL-17A production and decreased IL-22 levels in CD4+ T cells of vitiligo patients." (PMID 35625824, 2022). "Whether this implicates the IL-22 pathway in vitiligo pathogenesis remains unknown as IL22 transcripts were below the detection limit." (PMID 30515176, 2018). "Our results collectively indicated that IL-22 may potentiate IL-1β-mediated skin inflammation and result in participating in the inflammatory pathogenesis of vitiligo." (PMID 29312598, 2017). "However, upregulation of IL22 in the PBMCs of vitiligo patients has been reported earlier." (PMID 30515176, 2018). "Patients with vitiligo exhibit greater serum levels of IL-22 when compared to control individuals without vitiligo." (PMID 37275386, 2023). "No studies have evaluated the effectivity of IL-22 antibodies in vitiligo." (PMID 39201060, 2024).
acute kidney injury (8 papers, 2018 to 2026). Sudden and sustained deterioration of the kidney function characterized by decreased glomerular filtration rate, increased serum creatinine or oliguria. "IL-22 sustains epithelial integrity in progressive kidney remodeling and fibrosis during acute kidney injury." (PMID 32338120, 2020). "This study now shows the role of one such proregeneratory factor, namely IL‐22, beyond acute kidney injury in chronic progressive obstructive nephropathy." (PMID 30156011, 2018). "Therefore, except acute kidney injury, Il-22 can also play a protective role in chronic kidney disease." (PMID 32338120, 2020). "Notably, there is a growing evidence demonstrating that IL-22 possesses a therapeutic potential for acute kidney injury by targeting renal tubular epithelium." (PMID 31616439, 2019). "Furthermore, IL-22 ameliorated renal injury and accelerated tubular regeneration and recovery by targeting proximal tubule epithelium in acute kidney injury." (PMID 31616439, 2019). "In addition, it should be noted that macrophages have an important contribution to endogenous repair mechanisms after acute kidney injury, by several pathways, for example by secreting cytokines such as IL-22 and by providing ligands for retinoic acid (RA) and canonical Wnt-b catenin signaling." (PMID 31513644, 2019). "In the pathophysiology of acute kidney injury (AKI), hypoxia-inducible factor (HIF-1α) is expressed in renal tubular cells and can increase the secretion of IL-22 through the activation of CD4+ T cells, thereby regulating glucose metabolism and increasing glycogen storage." (PMID 35432360, 2022).
Anxiety (8 papers, 2020 to 2026). Intense feelings of nervousness, tension, or panic often arise in response to interpersonal stresses. "Stress‐induced intestinal IL‐22 crosses into septal brain regions to inhibit neuronal activation, which is both necessary and sufficient for alleviating anxiety‐like behaviors in mice." (PMID 41583906, 2026). "GBA dysfunction is associated with multiple disorders, and microbiota and their metabolites influence brain function via vagal signaling and immune mediators (e.g., IL‐22), offering novel perspectives on stress, mood disorders (depression, anxiety), and neurodegeneration (PD)." (PMID 41583906, 2026). "In a mouse model of PI-IBS, the AhR/IL-22 signaling pathway shows reduced expression, but administering IL-22 helps restore intestinal permeability and colonic sensitivity, enhances cognitive function, and lessens anxiety-like behavior." (PMID 41019044, 2025). "IL-22 delivering alleviate PI-IBS symptoms as colonic hypersensitivity, cognitive impairments, and anxiety-like behaviors by acting on intestinal mucosa integrity." (PMID 35090380, 2022).
autoimmune polyendocrine syndrome type 1 (8 papers, 2014 to 2025). Autoimmune polyendocrinopathy type 1, or APECED syndrome, is a genetic disease that manifests in childhood or early adolescence with a combination of chronic mucocutaneous candidiasis, hypoparathyroidism and autoimmune adrenal failure. "Interestingly, mucocutaneous candidiasis has been seen in association with anti-IL-17 and anti-IL-22 autoantibodies in autoimmune polyendocrinopathy candidiasis ectodermal dystrophy (APECED) syndrome, caused by a Mendelian deficiency of the autoimmune regulator (AIRE) gene." (PMID 25426445, 2014). "Mutations in AIRE resulting in autoimmune polyglandular syndrome type 1 (APS1) are associated with the formation of autoantibodies against IL‐17A, IL‐17F, and IL‐22 and CMC." (PMID 32609955, 2020). "An antibody panel can help orient toward an autoimmune etiology and therefore toward APECED syndrome at the early stage of the disease, even if the specificity and sensitivity of some antibodies were not as good as previously reported, with IL-22 seeming the most frequently identified in CMC." (PMID 38605470, 2025).
eczema (8 papers, 2013 to 2024). "Low IL-22 levels in umbilical cord blood may be linked to the development of infant eczema within 42 days, indicating a potential predictive value, although this value appears to be limited." (PMID 38606371, 2024). "This study aims to investigate the predictive value of umbilical cord blood IL-22 levels on the onset of eczema in infants within 42 days." (PMID 38606371, 2024). "Recent advancements have shown that inhibiting IL-22 expression can effectively treat eczema, and IL-22 has emerged as a crucial factor in eczema evaluation and treatment." (PMID 38606371, 2024). "The level of IL-22 in the umbilical cord blood of the eczema group was lower than that of the non-eczema group (p < 0.05)." (PMID 38606371, 2024). "The levels of IL-22 in the skin of children with eczema are considerably higher than in adults and correlate significantly with disease activity." (PMID 38606371, 2024). "Future studies should increase the sample size, measure additional cytokines in cord blood, extend the follow-up period, and examine venous blood IL-22 levels at different ages to elucidate its role in eczema more comprehensively." (PMID 38606371, 2024). "The occurrence of eczema is related to helper T 22 (Th22) cytokine disorder, and Th22 mainly secretes interleukin-22 (IL-22)." (PMID 38606371, 2024). "The ROC curve of cord blood IL-22 levels and infant eczema showed that the cut-off value is 36.362 pg/ml, the area under the curve (AUC) is 0.613, the standard error is 0.045, the 95% CI is 0.526–0.701, the sensitivity is 63.4%, and the specificity is 57.0%." (PMID 38606371, 2024). "Cord blood was collected immediately after birth to determine IL-22 levels, and the infants were followed up for 42 days to assess the incidence of eczema." (PMID 38606371, 2024). "The statistical analysis indicated that the level of IL-22 in the umbilical cord blood of the eczema group was lower than that in the eczema-free group." (PMID 38606371, 2024). "This analysis indicates that IL-22 levels are a significant factor in the occurrence of infant eczema at 42 days old (p < 0.05)." (PMID 38606371, 2024). "Researchers should also collect venous blood at these time points to further investigate the role of IL-22 in eczema development." (PMID 38606371, 2024). "Comparison of cord blood IL-22 levels between mild and moderate eczema." (PMID 38606371, 2024). "Additionally, reduced levels of IL-22 in umbilical cord blood moderately predict the occurrence of 42-day infant eczema." (PMID 38606371, 2024). "Logistic regression analysis and ROC curve results suggest that low umbilical cord blood IL-22 levels may play a role in the development of infant eczema within 42 days, indicating a limited predictive value." (PMID 38606371, 2024). "Therefore, there is a certain correlation between cord blood IL-22 levels and the incidence of infant eczema." (PMID 38606371, 2024). "Consequently, we explored the potential role of IL-22 in eczema's etiology, hypothesizing that its levels in neonatal cord blood could serve as an early marker of immune function." (PMID 38606371, 2024). "Existing literature indicates that IL-22 may contribute to skin inflammation in eczema patients." (PMID 38606371, 2024). "This suggests that reduced IL-22 levels could be a predictive factor for the early onset of eczema." (PMID 38606371, 2024). "Yet, no studies have explored the correlation between IL-22 levels in umbilical cord blood and the onset of eczema in 42-day-old infants." (PMID 38606371, 2024). "Our findings revealed significantly lower IL-22 levels in the cord blood of infants with eczema compared to those without the condition." (PMID 38606371, 2024). "Th17 cytokines dominate IL-22 production in early immune processes, and their levels in the cord blood of infants in the eczema group were lower than in those without eczema." (PMID 38606371, 2024).
eczema (continued). "Furthermore, our findings indicate that IL-22 levels do not correlate with the severity of early infant eczema, likely because the cases studied were predominantly mild to moderate." (PMID 38606371, 2024).
emphysema (8 papers, 2022 to 2025). "Airway microbiome-derived IAA mitigates neutrophilic inflammation, apoptosis, emphysema and lung function decline, via macrophage-epithelial cell cross-talk mediated by interleukin-22." (PMID 39233908, 2024). "For example, the indole IAA produced by Lactobacillus alleviates neutrophil inflammation, cell apoptosis, emphysema and lung function decline through IL-22-mediated macrophage-epithelial cell interaction." (PMID 39233908, 2024). "A COPD study showed that IL-22 mitigated neutrophilic infiltration, apoptosis, and emphysema and prevented a decrease in lung function." (PMID 39687635, 2024). "In a mouse model pulmonary neutrophilic inflammation, airway remodelling and emphysema were reduced and lung function was improved in IL‐22 KO mice exposed to cigarette smoke compared to WT controls." (PMID 39073027, 2024). "IL-22-deficient mice did not develop cigarette smoke–induced airway remodeling and emphysema-like alveolar enlargement." (PMID 41357311, 2025). "To explore the role of IL-22 in the COPD mouse model and the protective effects of AG490 and fezakinumab on emphysema, we evaluated the expression of IL-22R1 in mouse lung tissue using immunohistochemistry." (PMID 41357311, 2025). "T-helper cells are characterized by the production of IL-17A, IL-17F, and IL-22, which can be released by eosinophils, neutrophils, CD8+ T cells, basophils, and mast cells, also playing a decisive role in experimental models of emphysema treated with elastase." (PMID 37834157, 2023).
enteritis (8 papers, 2016 to 2025). Inflammation of the small intestine. "Our data indicate that oral administration of the probiotic BLS-mix partially ameliorates E. coli-induced enteritis through facilitating upregulation of intestinal IL-22 and IκBα expression, and preventing loss of intestinal epithelial barrier integrity via elevating ZO-1 expression." (PMID 27424033, 2016). "Our data above show that T cell–autonomous A20ZF7 functions and IL-22 are integral to enteritis in A20ZF7 mice." (PMID 40892518, 2025). "While deletion of IL-17A from A20ZF7/ZF7 mice exacerbates enteritis, deletion of IL-22 abrogates intestinal epithelial cell hyperproliferation, barrier dysfunction, and alarmin expression." (PMID 40892518, 2025). "In this study, we unveil a unique role for A20’s M1-Ub–binding motif in restraining epigenetic regulation of IL-22 expression in Th17 cells, intestinal epithelial cell homeostasis, and microbe-dependent enteritis." (PMID 40892518, 2025). "We unveil a novel pathophysiological pathway from A20’s ZF7 motif to RORg expression, regulation of a distal IL-22 enhancer in TH17 cells, and IL-22-and-microbe driven enteritis." (PMID 40892518, 2025). "Our studies uncover a new spontaneous model of proximal enteritis that links A20’s M1-Ub–binding motif to pathogenic Th17 cell activation, IL-22–dependent epithelial dysfunction, microbe-dependent enteritis, and epigenetic regulation of Il22 transcription." (PMID 40892518, 2025). "Compared with WT enteritis mice, Gpr43-/- enteritis mice showed higher expression of IL-6 and IL-22 and more tissue damage." (PMID 39741950, 2024). "Our studies highlight the ability of IL-22 to drive proximal enteritis." (PMID 40892518, 2025). "Our findings showed that the DSS experimental model developed using medaka larvae may be a viable option for basic research on IBD and also suggested the involvement of IL-22-mediated signals in the pathophysiology of enteritis in medaka." (PMID 34759916, 2021). "Co‐culture with intraperitoneal macrophages from mice with DSS‐induced enteritis significantly increased the levels of inflammatory factors (IL‐6, IL‐11, IL‐22, TNF‐α) in colonic epithelial cells compared to macrophages from healthy mice, whereas GW4868 eliminated this difference." (PMID 33569850, 2021). "Besides, the significant anti-viral activity of IL-22 could be a novel therapeutic against multiple enteric diarrhea viruses in IPEC-J2, such as PEDV, PoRV and TGEV, which were mediated by the activation of the STAT3 signal pathway." (PMID 37924089, 2023). "We have found that IL-22 stimulates exaggerated IEC elaboration of alarmins, hyperproliferation of crypt IECs, and compromised epithelial permeability, leading to microbe-dependent enteritis." (PMID 40892518, 2025).
eosinophilia (8 papers, 2013 to 2025). "Furthermore, eosinophilia plays a role in this mechanism, yet it was significantly reduced during infection in IL-22-deficient animals." (PMID 39635124, 2024). "The association of IL-9 and IL-22 with eosinophilia, and the decrease in these two cytokines with cows’ milk elimination, suggests that they both play a role in the symptoms observed in CMA and may be important targets for future interventions." (PMID 28934137, 2017). "However, both of these cytokines, and IL-22, were linearly positively associated with the extent of eosinophilia." (PMID 28934137, 2017). "The positive correlation of IL-22 concentration with eosinophilia in the current study, and the decrease in IL-22 with CM elimination, suggest a role for this cytokine in the on-going pro-inflammatory state that exists in CMA." (PMID 28934137, 2017). "For example, in a model of allergic airway inflammation, IL-22 decreased eosinophilia and Th2 cytokine production." (PMID 23472158, 2013). "Furthermore, IL-22 is correlated with the R265-induced eosinophilia and a prompter Th2 profile activation." (PMID 39635124, 2024). "RoRγt expressing ILC3 produce IL17 and IL22, both of which can contribute to eosinophilia and granulocyte recruitment, which may explain the reduced the reduced numbers of granulocytes in the mucosa of Rorc-/- x TRAG mice compared to TRAG mice." (PMID 38512959, 2024). "Eosinophilia suppression by rAg85B administration was reversed by neutralizing IL-22 Abs treatment." (PMID 25192550, 2014). "Moreover, the imbalance between IL-22 and IL-22R1 expression could influence local eosinophilia and disease severity through modulation of MUC1-dependent mechanisms." (PMID 41295249, 2025). "Notably, eosinophilia was disfavored in the absence of IL-22, a phenomenon that was associated with less IL-13 production." (PMID 39635124, 2024). "Therefore, the absence of IL-22 sustains the infiltrating inflammatory cell population during the infection, avoiding lung eosinophilia." (PMID 39635124, 2024). "In PBS control groups, Tg(−) and IL-22 Tg(+) mice showed no airway inflammation or eosinophilia." (PMID 25254361, 2014).
experimental autoimmune encephalomyelitis (8 papers, 2011 to 2024). An autoimmune demyelinating disease of the central nervous system that is produced experimentally in animals by the injection of homogenized brain or spinal cord in Freund's adjuvant. "Alternatively, Ahr-deficient mice exhibit IL-22 reduction, which is consistently found in an experimental autoimmune encephalomyelitis model." (PMID 31683543, 2019). "In experimental autoimmune encephalomyelitis (EAE), IL-22 was postulate to contribute to the pathogenic function of Th17 cells and IL-22 producing Th17 cells were the highly pathogenic population of self-reactive T cells." (PMID 24312440, 2013). "By contrast, IL-17 and IL-22 could be detected in inflammatory positive control, lymph node derived from experimental autoimmune encephalomyelitis mouse (data not shown)." (PMID 21949734, 2011).
Psoriasiform dermatitis (8 papers, 2013 to 2025). A skin abnormality characterized by redness and irritation, with thick, red skin that displays flaky, silver-white patches (scales). "Pharmacological restoration of the axis also has a proof-of-concept: a stable form of galectin-9 (a TIM3 ligand) suppresses contact hypersensitivity and IL-23–driven psoriasiform dermatitis, reducing IL-17/IL-22 and epidermal STAT3 activation." (PMID 41307843, 2025). "Resolvin D1 alleviated the IMQ-induced psoriasiform dermatitis and reduced the expression of IL-23, IL-17A, IL-17F, IL-22, and TNF-α in the lesions." (PMID 32751360, 2020). "We further investigated IL-38 potential in IMQ-induced psoriasiform dermatitis, an IL-17/IL-22-mediated mouse model of the disease." (PMID 30377293, 2018). "To assess the impact of CD103 on the regulation of the axis of IL-22-IL-23-IL-17 cytokine, we compared the induction of IL-17A- and IL-22-producing lymphocytes in the skin-draining PLNs between WT mice and Cd103−/− mice following initiation of psoriasiform dermatitis." (PMID 32433498, 2020). "In addition, IL-9 may induce IL-17- or IL-22 producing γδ T cells in the skin as these cells have been recently reported to play a critical role in IL-23-induced psoriasiform dermatitis in mice." (PMID 23335955, 2013). "We show here that adult mice treated with antibiotics that target Gram-negative and Gram-positive bacteria develop ameliorated psoriasiform dermatitis induced by imiquimod, with decreased pro-inflammatory IL-17- and IL-22-producing T cells." (PMID 26416167, 2015).